IKBKB-DT (IKBKB divergent transcript)
Synonyms: RP11-231D20.2; ALAL-1; IKBKBAS
Gene: Long non-coding RNA gene on chromosome 8 (42,233,662 to 42,271,275, reverse strand). Ensembl gene ENSG00000253408.
Diseases named in the same sentence as IKBKB-DT in open-access papers:
IKBKB-DT is named in the same sentence as 5 diseases in open-access papers, as found by Europe PMC text mining. Sharing a sentence is not in itself a finding about the gene and the disease.
IKBKB-DT shares sentences with these, for which no sentence is quoted: lung carcinoma (3 papers); lung adenocarcinoma (2); tumor (2); cancer (1); liver cancer (1).